USP22 (ubiquitin specific peptidase 22)
Diseases named in the same sentence as USP22 in open-access papers (continued):
Sharing a sentence is not in itself a finding about the gene and the disease.
tumor (continued). "In particular, we were interested to investigate whether Usp22 expression was differently modulated between well oxygenated and hypoxic tumor areas." (PMID 35626719, 2022). "Moreover, USP22 regulates necroptosis in tumor cells via governing receptor-interacting protein kinase 3 (RIPK3) stability." (PMID 35692754, 2022). "However, the roles of depth of invasion, GC differentiation and tumor size for USP22 expression in GC patients need to be analyzed in a larger and randomized controlled trial sample." (PMID 35784926, 2022). "They found that tumor growth was obviously reduced after the USP22 gene was knocked out." (PMID 35784926, 2022). "One of these tumor intrinsic epigenetic factors in PDAC is ubiquitin-specific protease 22 (USP22), which is suggested to control the immune TME through transcriptional regulation; thus, future inhibition of USP22 may turn the tumor sensitive to ICI." (PMID 35158814, 2022). "Studies have found that USP22 deletion may lead to a significant reduction of MDSCs in the TME and promote the infiltration of T cells and NK cells while the expression of USP22 confers tumor resistance to immunotherapy." (PMID 35924159, 2022). "Further understanding of the regulatory mechanism of USP22 expression may help to improve anti-tumor therapy." (PMID 35935969, 2022). "Considered as an oncogenic factor, the deubiquitinase USP22 links to tumor development." (PMID 34753387, 2021). "Furthermore, Han also proved that USP22 can promote tumor development through deubiquitination and immunosuppression in lung adenocarcinoma." (PMID 34179009, 2021). "However, its role as an intermediate pathway between KCNQ1OT1 and USP22 to regulate tumor immune escape is the first report and verification in this study." (PMID 34350172, 2021). "Together, our data suggest that therapeutic strategies targeting USP22 activity may sensitize tumor cells to UPR induction and could provide a novel, effective approach to treat HER2+-BC." (PMID 34007022, 2021). "The tumor-promoting function of USP22 has been reported in various malignant diseases." (PMID 33920268, 2021). "Downregulation of USP22 suppresses OS tumor growth and metastasis in vivo." (PMID 34571917, 2021). "USP22 favoured tumour cell proliferation, migration and invasion in vitro and in vivo." (PMID 34226501, 2021). "To address whether overexpression of Usp22 is sufficient to induce tumor formation in mice, we examined cohorts of WT, OE/+, and OE/OE mice for at least 2 years." (PMID 34503086, 2021). "Much evidence has shown USP22 is overexpressed in a variety of tumours but if it is protumourigenic posing a contradictory outcomes and investigation of its role in CCA remains completely unknown." (PMID 34226501, 2021). "However, we and others have demonstrated that USP22 can exert tumor-suppressive functions, putting the benefit of USP22 inhibition into question." (PMID 33920268, 2021). "RNF220 regulated BMI1 expression through USP22, promoting tumor growth in vivo." (PMID 34753387, 2021). "Our findings, therefore, demonstrate a critical tumor-promoting role of USP22 in HER2-driven BC." (PMID 34007022, 2021). "Interestingly, USP22 has been reported to promote tumor cell stemness and development by stabilizing BMI1." (PMID 34753387, 2021). "Among them, the tumor-promoting effect of lncRNA KCNQ1OT1 is through the autocrine effect of tumor cell-derived exosomes, which mediates the miR-30a-5p/USP22 pathway to regulate the ubiquitination of PD-L1 and inhibits CD8+ T-cell response, thereby promoting CRC development." (PMID 34350172, 2021). "Together, the evidence above clearly shows the roles of USP22 in driving tumor growth." (PMID 33805973, 2021). "USP22 upregulation affects a broad range of pathways in NSCLC to maintain tumor aggressiveness." (PMID 34660907, 2020). "Meanwhile, tumor volume and tumor weight is significantly reduced upon stable USP22 knockdown." (PMID 32665011, 2020).
tumor (continued). "In pancreatic cancer, in addition to affecting tumor progression through the regulation of the cell cycle, USP22 can also influence tumorigenesis and development by regulating immune cell infiltration through nuclear functions independent of its effects on PD-L1 protein stability." (PMID 32850399, 2020). "PD-L1 function as immune checkpoint to inhibit cytotoxic T cell-mediated tumor killing, we asked whether USP22 depletion suppressed tumorigenesis." (PMID 32665011, 2020). "Similar results were observed in tumor tissue derived from USP22-overexpressing SGC7901 cells." (PMID 32063746, 2020). "Despite the fact that the majority of studies report oncogenic properties of USP22, we and others have discussed that USP22 might display tumor-suppressive functions in some biological contexts." (PMID 31801945, 2019). "In addition, high USP22 expression correlated positively with tumor size, advanced stage and metastasis, and correlated negatively with tumor differentiation and prognosis in GC patients." (PMID 31689236, 2019). "Moreover, high USP22 expression in GC tissues positively correlates with tumor size, local lymph node metastasis, distant metastasis, and histological grades, and negatively correlates with GC differentiation and prognosis." (PMID 31689236, 2019). "Based on experimental evidences showing beneficial effects related to knockout of USP22 on tumor progression and to inhibition of acetylation we might envisage treatments with KAT and Ub-related inhibitors as active compounds counteracting tumor progression." (PMID 30524288, 2018). "In particular, we will present the oncogenic properties associated with USP22 overexpression in transcription activation, cell death and cell cycle progression and then will describe the putative tumor suppressor role of USP22 in the preservation of genome stability." (PMID 29210986, 2017). "Characterizing the oncogenic and tumor suppressor functions of USP22 and its impact on H2Bub1 is essential for the development of precision medicine therapies tailored to the specific genetic context of patients with altered USP22 expression." (PMID 29210986, 2017). "Our previous work has demonstrated that increased expression of USP22 in HCC might be important for tumor progression and can serve as an independent biomarker for poor survival." (PMID 28445968, 2017). "The molecular mechanism of USP22 involving in tumor metastasis was next deciphered." (PMID 27145278, 2016). "Consistently, USP22 knockdown resulted in suppressed tumor growth and metastasis of ATC in vitro." (PMID 27145278, 2016). "Molecular analysis of the tumor tissues showed that USP22 knockdown reduced the levels of cyclin D2, Akt phosphorylation, vimentin, and Bcl-2, whereas upregulated the expressions of E-cadherin, Bax, and cleaved (cl)-caspase-3, which confirmed in vitro findings." (PMID 27145278, 2016). "In summary, this study demonstrates that USP22 expression is significantly increased in HCC tissues and that the increased USP22 expression in human HCC might be important for tumor progression and can serve as an independent biomarker for poor survival." (PMID 25909224, 2015). "The results indicated that high USP22 expression promotes tumor progression in HCC." (PMID 25909224, 2015). "Furthermore, tissue-specific ablation of Usp22 alone or in the context of mouse tumor models will be essential for determining its function both in individual tissues as well as in the context of tumor formation and progression." (PMID 26431380, 2015). "Furthermore, correlation analysis demonstrated that high USP22 expression was correlated with clinical stage (p= 0.002 for the training set and p= 0.026 for the test set) and tumor grade (p= 0.004 for the training set and p = 0.001 for the test set)." (PMID 25909224, 2015). "USP22 knockdown significantly inhibited tumor growth in nude mice." (PMID 27030811, 2015).
tumor (continued). "Furthermore, we divided tumor samples into two groups on the basis of USP22 amounts and studied the differences of SOX2 expression." (PMID 24466336, 2014). "Finally, we confirmed that over-expression of Sp1 inhibited the endogenous USP22 expression in human tumor cells." (PMID 23300749, 2012). "Based on these findings, we initially hypothesized that Sp1 might play a positive role in USP22 gene transcription, since USP22 is up-regulated in most human tumor cells." (PMID 23300749, 2012). "However, the regulatory mechanism underlying USP22's tumour biological processes has not yet been thoroughly elucidated." (PMID 41909123, 2026). "Notably, USP22 has been reported to participate in cell cycle regulation, invasion and metastasis, immune regulation, stemness maintenance and chemoresistance of types of tumour cells." (PMID 40341781, 2025). "Furthermore, IHC staining confirmed the reduced EZH2 expression in Usp22-null tumor cells." (PMID 41252204, 2025). "Decreased PD‐L1 expression in the tumor environment after USP22 knockdown was found and the upregulation effects of PD‐L1 and USP22 induced by Taz or immunotherapy were also attenuated, which suggested that USP22 is involved in EZH2‐mediated regulation of PD‐L1 expression." (PMID 38520088, 2024). "Whether Usp22 loss in pretumor cells might impact tumor formation through changes in the UPR is not yet clear." (PMID 38236941, 2024). "Moreover, USP22 regulates endocytosis of tumor cells and localizes to late endosomes." (PMID 39101247, 2024). "Therefore, high USP22 expression in tumor tissues could predict the benefit of sirolimus in patients with HCC after LT, which supports the significant role of USP22 in activating mTORC1 in HCC." (PMID 38045832, 2023). "Importantly, it has been recognized that VEGFA also plays a crucial role in tumor immunosuppression, and our results suggest that USP22 may participate in tumor immune escape via modulation of VEGFA expression." (PMID 36906615, 2023). "Furthermore, USP22 plays a part in regulating the tumor microenvironment." (PMID 37415977, 2023). "In addition, lncRNA KCNQ1OT1, which is overexpressed in tumor tissues and tumor cell-derived exosomes, could regulate PD-L1 ubiquitination via the miR-30a-5p/USP22 pathway, thereby promoting CRC immune escape." (PMID 37760852, 2023). "This suggests that USP22 may regulate tumor resistance to immunotherapy." (PMID 35935969, 2022). "Furthermore, mice implanted with either the shControl MHCC-97H cells or the MHCC-97H cells with simultaneous USP22 knockdown and PPARγ overexpression showed similar tumor growth rates, whereas mice bearing the USP22-knockdown MHCC-97H cells showed markedly inhibited tumorigenesis." (PMID 35449157, 2022). "However, how the deubiquitinases (CSN5, USP9X, USP21, OTUB1, and USP22) coordinatePD-L1 protein level in response to distinct tumor microenvironment signals remains unknown." (PMID 34741014, 2021). "In other words, USP22 may inhibit the immune response to tumor cells by directly acting on FOXP3." (PMID 34179009, 2021). "Besides regulating the UPR, the identification of USP22-enzymatic activity in the ER may have further consequences for tumor cell aggressiveness." (PMID 34007022, 2021). "Loss of USP22 expression delays TNFα/carbobenzoxyvalyl‐alanyl‐aspartyl‐[O‐methyl]‐fluoromethylketone (zVAD.fmk)/Smac mimetic‐induced necroptosis in several human tumor cells, without affecting TNFα‐induced nuclear factor‐kappa B (NF‐κB) signaling or TNFα‐mediated extrinsic apoptosis." (PMID 33369872, 2021). "However, whether SIRT1 is pro- or anti-tumour growth, particularly its involvement in CCA associated with USP22, remains unknown." (PMID 34226501, 2021). "Moreover, an injection of tumor cells (EG7, B16 and LLC-1) in mice with Usp22-deficient Tregs reduced tumor development through the downregulation of the Treg suppressive functions and their abundance in the TME, consequently enhancing the antitumor immune response." (PMID 33924428, 2021).
tumor (continued). "However, novel roles for USP22 have emerged recently, such as tumor development and cell death." (PMID 33369872, 2021). "Analyses of these mice clearly show that while Usp22 overexpression alters several tumor-related signaling pathways and induces associated morphological changes such as hyperbranching of the mammary gland, Usp22 overexpression alone is not sufficient to induce tumorigenesis." (PMID 34503086, 2021). "Moreover, the depletion of USP22 was shown to decrease in vivo tumor growth." (PMID 34660907, 2020). "We confirmed that USP22 could participate in the interaction between tumor cells and immune cells." (PMID 32294625, 2020). "Therefore, our results demonstrated a new role of USP22 in regulating tumor immunosuppression." (PMID 32665011, 2020). "Finally, USP22 promotes tumor formation in vitro and in xenograft nude mice." (PMID 27030811, 2015). "Finally, we discover that USP22 knockdown leads to slower cell growth and reduced tumor size." (PMID 27030811, 2015). "Therefore, advancing our understanding of how the SAGA DUB module controls cell division may provide insights into the role of USP22 in tumor progression." (PMID 24948786, 2014). "However, the mechanisms leading to USP22 transcriptional activation, particularly in human tumor cells, are still unknown." (PMID 23300749, 2012). "Consistent with 4T1 R model, inhibition of Usp22 in LLC1 cells, a well-established syngeneic tumor model that is resistant to ICB, inhibited tumor growth." (PMID 41252204, 2025). "Conversely, targeted deletion of Usp22 resulted in enhanced EZH2 ubiquitination both RM1 and MC38 tumor cells." (PMID 41252204, 2025). "Consistent with our findings that USP22 protects EZH2 from ubiquitination-mediated degradation, both USP22 and EZH2 proteins were highly expressed and positively correlated in tumor tissues compared with adjacent normal tissues." (PMID 41252204, 2025). "Mechanistically, USP22 stabilizes SIRT1 via deubiquitination, subsequently activating the TAK1/Akt-ERK signaling axis to drive tumor progression." (PMID 41301681, 2025). "Similar to the CRISPR-targeted Usp22 inhibition, USP22i-S02 treatment synergized with anti–PD-1 resulted in a nearly complete inhibition of both RM1 and MC38 tumor growth with increased CD8 antitumor immunity." (PMID 41252204, 2025). "USP22‐mediated EV secretion contributes to invadopodia formation in LUAD cells, which in turn promotes tumor cell invasion." (PMID 39101247, 2024). "After USP22 knockdown, overall infiltration of early‐stage exhausted PD‐1 + CD8+T‐cell was comparable to the wild‐type MC38 tumor model, and t a mild tendency of enhancement of infiltration of PD‐1+ CD8+T‐cell was observed after Taz treatment." (PMID 38520088, 2024). "Ubiquitin‐specific protease 22 (USP22), a member of the DUB family, plays various roles in the physiological functions of tumour cells, including DNA damage repair, cell proliferation, apoptosis and tumour stem cell maintenance and metabolism." (PMID 39661501, 2024). "However, the role of USP22 in the secretion of tumor cell‐derived EVs remains unknown." (PMID 39101247, 2024). "For instance, USP22, OTUB1, and CSN5 can prevent PD‐L1 on tumor cells from being ubiquitinated and degraded, which suppresses immune cells activity in the tumor microenvironment and enables cancer cells immune escape." (PMID 38938284, 2024). "Therefore, autophagy may inhibit tumor initiation by downregulating USP22 expression in HCC." (PMID 38045832, 2023). "We found that PDX 25 with high USP22 expression exhibited larger tumor volumes and was more sensitive to rapamycin than PDX 99 with low USP22 expression." (PMID 38045832, 2023).
tumor (continued). "We and others have demonstrated that USP22 is upregulated in multiple types of CSCs, and controls CSC self-renewal and tumor chemoresistance." (PMID 36333288, 2022). "Among them, the expression of USP22 and survivin was shown to be closely related to the malignant behavior of HCC cases, including tumor size, stage, and differentiation." (PMID 35875077, 2022). "Apart from USP22, USP44 has been shown to be upregulated in CSCs of breast cancer and promote tumor angiogenesis." (PMID 35924159, 2022). "It has been reported that USP2a, USP7, USP21, and USP22 are highly expressed in the HCC tissue or cells and promote tumor development." (PMID 35669517, 2022). "For example, lncRNAs can influence tumour invasiveness and resistance through the miR-302a-3p/AKT axis, miR-124-3p/MCP-1 pathway, or miR-132-3p/USP22 pathway." (PMID 36071865, 2022). "We found that USP22 depletion in HT29 and RKO E6 cells attenuated tumor formation, and reconstituted expression of FASN rescued the inhibitory effect of USP22 depletion on colorectal tumorigenesis." (PMID 36333288, 2022). "We next investigated the role of USP22-mediated stabilization of FASN in CRC cell proliferation and tumor growth." (PMID 36333288, 2022). "In pancreatic ductal adenocarcinoma (PDAC), knockdown of USP22 demonstrated better response to immunotherapy, with increased proportion of natural killer (NK) cells and CD8+ T cells in the tumor." (PMID 35935969, 2022). "Our present study defines USP22 as a poor prognostic predictor in iCCA that cooperates with SIRT1 and facilitates tumour development." (PMID 34226501, 2021). "We showed that USP22 protein expression by IHC was consistently upregulated in CCA, present predominantly in the tumour cell nucleus but rarely in any other subtypes of cells." (PMID 34226501, 2021). "Ubiquitin‐specific protease 22 (USP22) controls necroptotic cell death by regulating RIPK3 phosphorylation and RIPK3 K518 ubiquitination in human tumor cell lines." (PMID 33369872, 2021). "In agreement with this possibility, we show that diminished USP22 expression induces CIN, highlighting a novel role for USP22 as a tumor suppressor that is essential to maintain mitotic fidelity and chromosome stability." (PMID 33801331, 2021). "Regarding the growth of OS primary tumor, USP1, USP22 and USP39 have been shown to participate in the control of OS cell proliferation." (PMID 34571917, 2021). "In this study, we found that USP22 overexpression induces c-myc upregulation in both SGC7901 cells and tumor tissue, consistent with previous reports." (PMID 32063746, 2020). "Western blot analysis was conducted to detect the activation of RAS/ERK and PI3K/AKT signaling in USP22-overexpressing SGC7901 cells and xenograft tumor tissues." (PMID 32063746, 2020). "Western blot analysis showed that USP22 overexpression also induced activation of the RAS/ERK and PI3K/AKT pathways in SGC7901 cells and xenograft tumor tissues." (PMID 32063746, 2020). "More than that, knocking down USP22 can up-regulate STAT1 to activate JAK1-STAT1-caspase pathway, and promote apoptosis of tumor cell." (PMID 32294625, 2020). "However, how USP22 sense tumor microenvironment signals to regulate PD-L1 remains unknown." (PMID 32665011, 2020). "Evidently, various reports have shown the elevated expression of USP22, CBX6, NRAGE, ACTL6, and CHMP4B genes correlate with larger tumor size, advanced tumor stages, poor prognosis and short survival time of patients in LIHC." (PMID 31490960, 2019). "Thus, targeting USP22 could potentially have tumor-promoting effects." (PMID 31801945, 2019). "We performed tumor sphere assays and found that the inhibited chemoresistance by miR‐30‐5p in CRC cells was partially abolished by USP22 overexpression." (PMID 30338942, 2019). "Patients with high expression of USP22 and low expression of Smad4 significantly has lower AFP, smaller tumor size and higher TNM stage." (PMID 28445968, 2017).